PDXK (pyridoxal kinase)
Diseases named in the same sentence as PDXK in open-access papers (continued):
Sharing a sentence is not in itself a finding about the gene and the disease.
cancer (continued). "Evidence has shown that cuproptosis-related genes (e.g. PDXK, FDX1 and LIPT1) can affect the progression of human cancers." (PMID 39652607, 2024). "Eight proteins (A4GALT, ASIP, CTSF, MARE1, PDXK, SEM4A, PLAUR, VARS1) were observed to have evidence of multi-trait colocalization between the index protein, intermediate phenotypes, and the index cancer endpoint, which may serve to elucidate aetiological pathways to cancer risk." (PMID 38684708, 2024).
tumor (7 papers, 2020 to 2026). "Besides, the univariate Cox regression analysis identified five features (BCLC stage, portal vein tumor thrombus, TNM stage, tumor count, and PDXK expression) that were significantly associated with survival in clinical cohorts." (PMID 36750831, 2023). "Accordingly, high expression of PDXK and PNPO, two key genes involved in PLP biosynthesis, is associated with tumor progression in some malignancies, whereas it correlates with improved outcomes in others." (PMID 41898732, 2026). "Circular RNA FOXK2 aggravates PDAC tumor growth and metastasis by affecting PDXK and NUF2 expression through interaction with RNA binding protein YBX1 and hnRNPK." (PMID 38833016, 2024). "In summary, butyrate significantly inhibits the growth of BC tumor and facilitates the expression of PDXK and SLC25A28 in a dose-dependent manner." (PMID 38833016, 2024). "Among the five signature genes, the high expression of PDXK in HCC tumor samples were confirmed by the Western Blot and IHC, and the high expression of PDXK indicated a worse survival in our clinical cohorts." (PMID 36750831, 2023). "PDXK was also found to be upregulated in HCC tumor samples compared to the paired normal tissue by Western Blot." (PMID 36750831, 2023). "Mechanistically, PDXK knockdown significantly inhibited the tumor proliferation by retaining the cells in the G0/G1 phase." (PMID 36750831, 2023). "Furthermore, IHC was used to investigate the protein level of PDXK in 30 paired HCC tumor and normal specimens." (PMID 36750831, 2023). "Furthermore, the upregulation of PDXK was confirmed in HCC tumor tissues in 30 clinical HCC specimens." (PMID 36750831, 2023). "Moreover, decreased PDXK protein expression and decreased SLC25A28 protein expression were found in clinical BC tumor specimens." (PMID 38833016, 2024). "A previous study demonstrated that circFOKX2 not only interacts with YBX1 and hnRNPK to elevate the expression of the oncogenes NUF2 and PDXK but also functions as a sponge for miR-942 to upregulate the expression of ANK1, GDNF, and PAX6, which contribute to tumor progression in PDAC." (PMID 34419070, 2021). "Because the high protein levels of PDXK in the tumour did not correlate with the amounts of its mRNA, the authors suggested that PDXK expression is subjected to a post-translational control." (PMID 32208818, 2020).
PDXK also shares sentences with these, for which no sentence is quoted: peripheral neuropathy (2 papers); autistic disorder (1); cardiovascular disease (1); celiac disease (1); clear cell renal carcinoma (1); colon cancer (1); congenital heart disease (1); connective tissue disorder (1); coronary artery disease (1); hepatomas (1); Insulin resistance (1); ischemic stroke (1); Parkinson disease (1); peripheral nerve disease (1); psychiatric disorder (1); retinoblastoma (1); schizophrenia (1); Sensory neuropathy (1); uremia (1); virus infection (1).